PLA2G12B (phospholipase A2 group XIIB)
Description:
Not known; does not seem to have catalytic activity.
Synonyms: GXIIB; PLA2G13; FKSG71; GXIIIsPLA2; sPLA2-GXIIB
Tractability: Small molecule: a high-quality ligand is known. Antibody: UniProt places it where antibodies can reach, with medium confidence; UniProt predicts a signal peptide or a membrane-spanning region; its Gene Ontology location is reachable by antibodies, with medium confidence. PROTAC: its protein half-life has been measured; a small molecule that binds it is known.
Gene: Protein-coding gene on chromosome 10 (72,933,098 to 72,954,845, reverse strand). Ensembl gene ENSG00000138308.
Subcellular location: Secreted
Gene Ontology:
Molecular function: calcium ion binding; phospholipase A2 activity
Biological process: cholesterol homeostasis; triglyceride homeostasis; arachidonate secretion; lipid catabolic process; phospholipid metabolic process
Cellular component: extracellular region
Genetic constraint (gnomAD): Loss-of-function variants: 19 observed, 21.57 expected, observed/expected ratio (o/e) 0.88, 90% interval 0.61 to 1.29. The upper end of that interval is the gene's LOEUF score, 1.29, which puts it in group 5 of 6, group 1 being the genes least tolerant of losing a copy. Missense variants: 191 observed, 254.69 expected, observed/expected ratio (o/e) 0.75, 90% interval 0.67 to 0.85. Synonymous variants: 81 observed, 99.6 expected, observed/expected ratio (o/e) 0.81, 90% interval 0.68 to 0.98.
Homologues: Orthologues: chimpanzee PLA2G12B (100% identical), macaque PLA2G12B (98% identical), dog PLA2G12B (94% identical), guinea pig PLA2G12B (92% identical), pig PLA2G12B (91% identical), mouse Pla2g12b (90% identical), rat Pla2g12b (90% identical), rabbit PLA2G12B (88% identical), tropical clawed frog pla2g12b (73% identical), zebrafish pla2g12b (65% identical), Drosophila melanogaster GXIVsPLA2 (30% identical), Caenorhabditis elegans C31H1.5 (21% identical), and 1 more. Paralogues in human: PLA2G12A (41% identical).
Diseases named in the same sentence as PLA2G12B in open-access papers:
PLA2G12B is named in the same sentence as 11 diseases in open-access papers, as found by Europe PMC text mining. Sharing a sentence is not in itself a finding about the gene and the disease. The quoted sentences say what the papers report.
atherosclerosis (4 papers, 2012 to 2025). A disease characterized by the build-up of fatty material and calcium deposition in the arterial wall resulting in partial or complete occlusion of the arterial lumen. "Loss of PLA2G12B function therefore supports relatively normal growth and metabolism despite intestinal and hepatic lipid accumulation and profound serum hypolipidemia and resistance to atherosclerosis." (PMID 38453914, 2024). "While studies on the molecular mechanisms underlying atherosclerosis suggest increased OS, production of AGEs, and chronic inflammation, PLA2G12B-mutant mice are atherosclerosis-resistant." (PMID 40563358, 2025). "Thierer and colleagues identify PLA2G12B as a key gene driving triglyceride incorporation into lipoproteins and show that disruption of this activity provides protection from atherosclerosis." (PMID 38453914, 2024). "We also detect profound resistance to atherosclerosis in PLA2G12B mutant mice, suggesting an evolutionary tradeoff between triglyceride transport and cardiovascular disease risk." (PMID 38453914, 2024). "Finally, we evaluated the physiological consequences of PLA2G12B disruption, showing that Pla2g12bhlb218 mutants exhibit profound hypolipidemia and resistance to atherosclerosis coupled with otherwise normal growth and metabolism." (PMID 38453914, 2024).
deficiencies (1 paper, 2024). "Modulation of PLA2G12B activity may have particular therapeutic value for the treatment of familial lipase deficiencies, such as lipoprotein lipase (LPL) mutants." (PMID 38453914, 2024).
glioma (1 paper, 2024). A benign or malignant brain and spinal cord tumor that arises from glial cells (astrocytes, oligodendrocytes, ependymal cells). "PLA2G12B, a phospholipase A2 variant, is of interest, given recent evidence for the role of phospholipases in cancer and documented high expression levels in glioma, as well as its emergence as an oncogene associated with glioma progression." (PMID 38612892, 2024).
Hepatic steatosis (1 paper, 2012). Steatosis is a term used to denote lipid accumulation within hepatocytes. "The precise mechanism and the mode of the effect (direct or indirect) by which Pla2g12b dysfunction affects serum lipid levels and leads to hepatic steatosis must still be elucidated." (PMID 22912808, 2012).
hyperlipidemia (1 paper, 2024). "Notably, while this hyperlipidemia paradigm caused cholesterol levels to increase dramatically in Pla2g12b mutant mice (>100-fold increase), the increase in serum triglyceride levels was much less pronounced (~7-fold increase)." (PMID 38453914, 2024). "PLA2G12B therefore represents a potential therapeutic target to combat the growing global prevalence of hyperlipidemia and cardiovascular disease." (PMID 38453914, 2024).
idiopathic membranous nephropathy (1 paper, 2021). "PLA2G12B can also participate in the pathogenesis of idiopathic membranous nephropathy (iMN) by regulating lipid metabolism." (PMID 34573356, 2021).
tumor (4 papers, 2008 to 2023). "RT-qPCR and IHC indicated that the expression of GLS, NOX1, HOXC6, TNNT1 and PLA2G12B were up-regulated in tumor tissues, compared with those in normal tissues, and all of GLS, HOXC6, NOX1 and PLA2G12B were closely related with patient survival." (PMID 37333810, 2023). "PLA2G12B and RP11-73M18.2 are up-regulated in all tumor samples of any stage." (PMID 35659616, 2022). "No variation in expression between the tumours and normal mucosa was observed for PLA2G1B, PLA2G2A, PLA2G2F, PLA2G10, PLA2G12A and PLA2G12B and for the M-type sPLA2 receptor (PLA2R1)." (PMID 18212756, 2008).
infection (2 papers, 2010 to 2021). The state of being infected such as from the introduction of a foreign agent such as serum, vaccine, antigenic substance or organism. "Infection of mice with an adenovirus encoding Pla2g12b into Pla2g12b-/- mice improves hepatic VLDL secretion and restores the decline in serum TGs." (PMID 34512555, 2021).
cardiovascular disease (1 paper, 2024). "Our assessment of cardiovascular disease in PLA2G12B mutants provides experimental evidence that interfering with TRL expansion is atheroprotective." (PMID 38453914, 2024).
PLA2G12B also shares sentences with these, for which no sentence is quoted: cancer (1 paper); steatosis (1).